KCNMA1 (potassium calcium-activated channel subfamily M alpha 1)
Diseases named in the same sentence as KCNMA1 in open-access papers (continued):
Sharing a sentence is not in itself a finding about the gene and the disease.
pulmonary edema (1 paper, 2024). Accumulation of fluid in the lung tissues causing disturbance of the gas exchange that may lead to respiratory failure. "KCNC3, KCNQ3, and KCNMA1 are voltage-gated potassium ion channel proteins, and the downregulation of KCNC3 and KCNQ3 in yak lungs suggested that the expression of voltage-gated potassium ion channels decreases in yaks with age, reducing membrane depolarization and harmful effects of pulmonary edema." (PMID 38779034, 2024).
pulmonary fibrosis (1 paper, 2021). Chronic progressive interstitial lung disorder characterized by the replacement of the lung tissue by connective tissue, leading to progressive dyspnea, respiratory failure, or right heart failure. "The two most significant predictions from the SEA search for targets of niclosamide include KCNMA1 (calcium-activated potassium channel subunit alpha-1) and TMPRSS4 (transmembrane protease serine 4), both of which have been associated with pulmonary fibrosis." (PMID 34078171, 2021).
vascular occlusion (1 paper, 2022). "This is the first study showing that the low expression of genes associated with epigenetic regulation, such as SOX6 and RBM33, may be related to vascular occlusion in MMD, whereas the overexpression of KCNMA1 and GALNT2 may be related to the vascular hyperplasia." (PMID 35368875, 2022).
cancer (46 papers, 2010 to 2025). A tumor composed of atypical neoplastic, often pleomorphic cells that invade other tissues. "Such down-regulation is meaningful because KCNMA1 high expression has been associated with cell proliferation and poor prognosis in cancer." (PMID 25110883, 2014). "ChIP experiments show that the Sp1 occupies its binding sites in the promoters of XIAP, CRABP1, MDK, and KCNMA1, and that DIG-MSK decreases Sp1 binding to them with a superior effect on KCNMA1, a gene associated with high proliferation in cancer cells." (PMID 25110883, 2014). "For example, alteration of KCNMA1 function has been associated with several complex human disorders including cancer." (PMID 20830292, 2010). "And we found that one TF, E2F3 was related to ESCA, two genes, DTNA and KCNMA1 were related to STAD, while one TF ESR1 and one gene KIT were associated with both of the two types of cancer." (PMID 31888440, 2019). "The expression level of KCNMA1 in cancer tissues was significantly decreased compared with normal tissues (P = 0.008)." (PMID 28231797, 2017). "We also found a large number of genes functioning in the plasma membrane; four genes CHRNA3, CLIC1, KCTD1 and KCNMA1 were discovered in iron channel complex; except KCTD1, all others were associated with cancer." (PMID 26367387, 2015). "The prevalence of the amplification across different human cancer types points towards a broader general oncogenic potential of KCNMA1 than previously assumed." (PMID 22899999, 2012). "Our study reveals for the first time that KCNMA1 amplification is restricted to human cancer types that derive from tissues regulated by sex steroid hormones including prostate, breast, uterus, and ovary." (PMID 22899999, 2012). "In the present study, we examined the prevalence of the KCNMA1 amplification in the whole range of human cancer and analyzed a large multi-tumour TMA, containing 2445 tissue spots from 118 different tumour types by FISH, using a KCNMA1-specific BAC probe." (PMID 22899999, 2012). "The restriction of KCNMA1 amplification to carcinomas from sex hormone-regulated organs is highly intriguing and also suggests an interaction of KCNMA1 within the hormonal context of these tumours." (PMID 22899999, 2012). "In conclusion, we report for the first time that KCNMA1 amplification occurs in carcinomas of the breast, ovary and endometrium." (PMID 22899999, 2012). "KCNMA1, a large potassium (BK) ion channel, is a possible target for cancer immunotherapy." (PMID 36817484, 2023). "Besides, several genes (including MAMDC2, F2RL2, and KCNMA1) were enrolled as biomarker for the prognosis of varying cancers." (PMID 37313409, 2023). "To identify whether the cancer cell methylation directly mediates KCNMA1 expression, we treated the two cell lines (i.e., MGC-803 and BGC-823) with the demethylation agent, 5-Aza-2′-deoxycytidine (5-Aza; Sigma-Aldrich), for 72 h." (PMID 28231797, 2017). "KCNMA1 protein (also named BK) was the pore-forming α subunit of the α-subunit of the large conductance, voltage and Ca2+-activated K+ channel, and was thought to play several roles in cancer biology." (PMID 28231797, 2017). "Furthermore, it has been established that miR-211 directly targets potassium calcium-activated channel subfamily M alpha 1 (KCNMA1), a gene which is commonly associated with enhanced cell proliferation and increased migratory and invasive capabilities in various cancer types." (PMID 40869148, 2025). "In addition, we detected the expression of KCNMA1 in 75 paired of cancer and normal tissues." (PMID 28231797, 2017). "We also investigated four genes, RAI2, KCNMA1, NBEA, and KIT, in the two ranking lists, and their potential functions for these two types of cancer." (PMID 31888440, 2019).
cancer (continued). "In the present study, we have studied the expression of KCNMA1 in preclinical and human CRC and found that KCNMA1 is significantly downregulated in CRC, independently of the cancer stage." (PMID 30791468, 2019). "Word searches of PubMed for oncogene and histone publications related to those for H+, K+, BK (KCNMA1), and Cl− (contrasting ion), without and with “cancer”, were performed to further evaluate the categories." (PMID 40867621, 2025). "Similarly, seven genes (SGCZ, KANK1, KDM4C, KCNMA1, ZNF263, CDH4, NCAM2) contain partial CNV duplications in both BD‐cancer and BD‐only patients, but the deleted loci are different." (PMID 39140252, 2025). "Also, the PubMed citations for BK (KCNMA1 encoded) probably constituted a large proportion (approximately one-third) of studies involving K+ and H+ across the categories of seven oncogenes and “histone” not restricted to cancer and most of the studies when restricted to “cancer”." (PMID 40867621, 2025). "To address this issue, we assessed the expression of genes associated with metastatic ability and stem cell function such as KCNMA1 and ASPM, which has been reported earlier to serve as prognostic molecular markers of the metastatic process and cancer stem cell maintenance, respectively." (PMID 25796627, 2015). "Considering frequent silencing of KCNMA1 in primary cancers and GC cell lines but not in normal gastric tissues, it suggested that KCNMA1 may act as probably a tumor suppressor." (PMID 28231797, 2017). "Therefore, we could not test the prevalence and significance of KCNMA1 protein expression in a large number of clinical cancer specimens." (PMID 22899999, 2012).
tumor (43 papers, 2009 to 2026). "The aberrant KCNMA1 methylation status in GC tissues was associated with tumor sizes and depth of invasion." (PMID 28231797, 2017). "KCNMA1 amplification was significantly associated with high tumor stage, high grade, high tumor cell proliferation, and poor prognosis." (PMID 22899999, 2012). "Our results demonstrate that KCNMA1 amplification is associated with high tumour stage, high tumour grade, high tumour cell proliferation, and poor prognosis." (PMID 22899999, 2012). "KCNMA1 amplification was significantly associated with high tumour cell proliferation (defined as Ki67 LI>30%; p<0.002)." (PMID 22899999, 2012). "The upregulated genes including GAB3, SLC8A1, KCNMA1, and ZNF471 following CFP1 knockdown, were expressed at low levels in tumor tissues and were associated with favorable prognosis of LUAD patients." (PMID 37735441, 2023). "KCNMA1 has been used as a prognosis-related biomarker in several tumors and is strongly correlated with tumor metastasis and calcium channels." (PMID 35721115, 2022). "The promoter methylation of KCNMA1 was detected in 68.7% (77/112) of tumor tissues, compared with 16.2% (18/112) of normal tissues (P < 0.001)." (PMID 28231797, 2017). "KCNMA1 exerts a tumor suppressive function by regulating the PTK2 expression to activate the PI3K-AKT pathway." (PMID 28231797, 2017). "Extensive research has highlighted the involvement of KCNMA1 in diverse tumor processes." (PMID 38464749, 2024). "Differential expression levels of KCNMA1 in different cancer cells may reflect multiple-related functions in tumor growth." (PMID 36763212, 2023). "Overexpression of KCNMA1 promoted tumor progression in mouse model." (PMID 32612536, 2020). "Interestingly, KCNMA1, a critical tumor suppressor in GC has been shown to be inactivated by promoter region hypermethylation, and the anti-tumor effect of KCNMA1 is mediated through suppressing the expression of PTK2." (PMID 31959204, 2020). "However, in this study we found the KCNMA1 was down-regulated in the tumor tissues due to the methylation of promoter and played a tumor suppressor role." (PMID 28231797, 2017). "However, SAHA significantly enhanced the tumor initiating capacity and the expression of malignant genes such as KCNMA1, MORF4L2 and ASPM in the remaining living ALDHbr cells." (PMID 25796627, 2015). "We seek to demonstrate whether tumor developed using U87 MG cells with KCNMA1 down-regulation fail to elicit similar BTB permeability increase to Gd-DTPA following NS169 infusion compared to that of the wild type tumor." (PMID 23755013, 2013). "Interestingly, a positive AR expression was detected in 14 of 25 (56%) of the non-KCNMA1 amplified tumours but in only one of nine (11%) KCNMA1 amplified tumours (p<0.05)." (PMID 22899999, 2012). "The same co-dependency of p-BRAF and KCNMA1 levels was then also recognized in the HEK293T cell line, which was derived from non-tumor tissue with wt BRAF." (PMID 36763212, 2023). "Raised KCNMA1 then acts to repolarize the membrane potential and sustain p-BRAF levels, which promotes tumor cell proliferation." (PMID 36763212, 2023). "OLFM4, SPINK8, CRYAB, KCNMA1, TFAP2B, and TFF1 were significantly upregulated during tumor progression in P8‐2 CTCs." (PMID 33377642, 2020). "Four consistent genes were differentially expressed in tumor tissues compared to normal tissues: two Ca2+-activated channels coding genes were induced (KCNN4, TRPM2) while KCNMA1 and TRPM6 were downregulated during the malignant transformation." (PMID 31010205, 2019). "Another five genes that were up-regulated with tumor progression showed further increased expressions after chemotherapy (CRISP3, KCNMA1, BDNF, SLC22A4, SYN2)." (PMID 23451142, 2013). "The negative correlation for KCNMA1 between expression and tumor grade was in accord with four independent cohorts." (PMID 24053408, 2013).
tumor (continued). "Thus, the presence of the KCNMA1 amplification in tumour specimens and MFM223 might rather highlight KCNMA1 as a gene with oncogenic relevance, while mechanisms other than amplification seem to be responsible for KCNMA1 overexpression in most of these tumours." (PMID 22899999, 2012). "No significant changes in the expression levels of GNB5 and KCNMA1 were observed between HCC tissues and the paired non-tumor tissues, which was not consistent with meta-analysis." (PMID 27769251, 2016). "MITF is also needed for miR-211 expression, suggesting that the tumor-suppressor activities of MITF and/or TRPM1 may at least partially be due to miR-211's negative post transcriptional effects on the KCNMA1 transcript." (PMID 21072171, 2010).
neurological disorder (11 papers, 2018 to 2025). "Seventy-five unique variants in the KCNMA1 gene have been identified from individuals with neurological disorders." (PMID 40785052, 2025). "In this study, the KCNMA1 variants N999S and E656A (rs886039469 and rs149000684, respectively) were investigated from two individuals presenting with neurological disorders." (PMID 40785052, 2025). "Both GOF and LOF mutations in KCNMA1 have been associated with neurological diseases, resulting in a spectrum of moderate to severe abnormalities." (PMID 36503451, 2023). "With the progress in human genetics, more KCNMA1 variants that link to neurological disorders have been identified." (PMID 34744799, 2021). "Since the identification of the first disease-linked KCNMA1 mutation, the number of patients identified with neurological disorders and mutations in BK channels has increased." (PMID 31851553, 2020). "Missense SNPs in KCNMA1 have been related to human neurological diseases." (PMID 36503451, 2023). "Accurate genotype-phenotype correlation in KCNMA1 neurological disease, like other rare disorders, is limited by lack of access to patient neurons." (PMID 40785052, 2025).
movement disorder (8 papers, 2021 to 2025). Neurological conditions resulting in abnormal voluntary or involuntary movement, which may impact the speed, fluency, quality and ease of movement. "New functional characterizations of BK channel activity from novel KCNMA1 variants suggest that PNKD could be more prevalent among GOF than LOF patients, while non-PNKD movement disorders are currently observed in higher proportion among LOF than GOF patients." (PMID 34224328, 2021).
adenocarcinoma (2 papers, 2015 to 2019). A common cancer characterized by the presence of malignant glandular cells. "However, as shown by PCA analysis, a high variance in the KCNMA1-associated methylation pattern can be observed among adenocarcinoma samples." (PMID 30791468, 2019).
gynecological tumours (1 paper, 2012). "Amplification of KCNMA1 was restricted to 10 of 603 (1.7%) gynecological tumours known to be influenced by estrogens." (PMID 22899999, 2012).
KCNMA1 also shares sentences with these, for which no sentence is quoted: cerebellar ataxia (7 papers); infection (6); schizophrenia (6); Anxiety (5); depression (5); erectile dysfunction (5); Hyperkalemia (5); overactive bladder (5); asthma (4); Cerebellar atrophy (4); Cognitive impairment (4); myocardial infarction (4); neuroblastoma (4); neurodevelopmental disorder (4); Seizure (4); benign prostatic hyperplasia (3); cardiovascular diseases (3); hearing loss (3); Hyperglycemia (3); renal fibrosis (3); Stroke (3); temporal lobe epilepsy (3); Tremor (3); triple-negative breast carcinoma (3); alcohol (2); Atrophy (2); brain ischemia (2); chondrosarcoma (2); chronic kidney disease (2); coronary artery disease (2).
A further 113 diseases each share a sentence with KCNMA1 in 2 papers or fewer.